INS (insulin)
Diseases named in the same sentence as INS in open-access papers (continued):
Sharing a sentence is not in itself a finding about the gene and the disease.
Obesity (continued). "For instance, diets high in fats and sugars appear to amplify BPA’s impact on obesity by accelerating lipid storage and insulin resistance, as BPA can disrupt metabolic tissues similar to natural estrogens, even at low doses." (PMID 39519574, 2024). "Our data are consistent with existing literature suggesting that adipose tissue eosinophils can reduce obesity and high insulin in mice on high-fat diets." (PMID 39316677, 2024). "In men with obesity, compared to those with normal body weight, statistically significant differences were observed in fasting serum levels of insulin, uric acid, LDL cholesterol, triglycerides, ALT, GGTP, and glucose levels after two hours in an OGTT." (PMID 39769504, 2024). "NEC1 affects several PCs, AF, and HF, and is a druggable protein that processes hormones such as insulin and its encoding gene PCSK1 associated with HF risk factors such as obesity and abnormal glucose homeostasis." (PMID 39434187, 2024). "According to a previous report, miR-27a participates in the regulation of genes involved in the insulin signalling pathway in models of obesity and after nutritional intervention." (PMID 39062958, 2024). "Therefore, therapeutic strategies targeting inflammation, particularly the pathways involved in caspase-1 activation—a key component of inflammasome activity—could represent a potential strategy to mitigate the chronic inflammation associated with obesity and improve insulin sensitivity." (PMID 39590865, 2024). "A study was conducted to investigate the effects of ASs on obesity in male Wistar rats, focusing on body weight, glucose levels, insulin, and leptin." (PMID 39449954, 2024). "In the field of immunology, much attention has been given to the low-grade inflammation detected in obesity and its metabolic repercussions, mainly involving insulin resistance." (PMID 39203559, 2024). "Recent research has shown a correlation between insulin action and magnesium levels, highlighting the link between low serum magnesium levels and obesity." (PMID 39429362, 2024). "Due to the multifaceted roles of MUFAs, alternations in SCD1 activity are expected to impact a variety of metabolic pathways, including those involved in insulin signal transduction and obesity." (PMID 38919749, 2024). "Although weight control is not one of the main concerns for persons with T1DM, nowadays, the prevalence of overweight and obesity is increasing in this group of patients due to sedentary lifestyle, increased caloric intake, and raised insulin doses." (PMID 38396657, 2024). "In line, previous studies indicate that SM 18:1/18:0, 18:1/20:0, 18:1/22:0 and 18:1/24:0 correlated with obesity, insulin resistance, liver function, and lipid metabolism." (PMID 38388533, 2024). "The metabolic and endocrine effects of a KD in women with obesity are characterized by improvements in body weight, free testosterone levels, the luteinizing hormone/follicle-stimulating hormone ratio, and fasting insulin levels." (PMID 38892561, 2024). "Daily injections of irisin over 8 weeks ameliorated development of the OVX/HFD-induced MetS phenotype, including improvements in obesity, energy expenditure, insulin sensitivity and lipid profile in comparison with OVX/HFD controls." (PMID 39040132, 2024). "Targeting the immunoproteasome highlights a promising therapeutic strategy to mitigate the detrimental effects of obesity on the insulin-glucose axis and cellular homeostasis." (PMID 39095788, 2024). "Resistance exercise also combats obesity and its complications by enhancing insulin signaling, reducing inflammatory responses, promoting favorable adjustments within the NADPH oxidase system, and improving the efficiency of insulin-mediated glucose clearance." (PMID 39334887, 2024). "Factors contributing to reduced insulin sensitivity in transplant recipients include age, male sex, obesity, and renal function." (PMID 38610694, 2024).
Obesity (continued). "The mechanisms of TCM intervention in obesity, including improving lipid metabolism, increasing insulin sensitivity, and reducing inflammatory responses, are well-documented." (PMID 39606109, 2024). "The study successfully induced obesity, resulting in worsened glucose tolerance and insulin sensitivity." (PMID 38611383, 2024). "Pathological damage to the pancreas was also ameliorated, indicating that zeaxanthin can reduce hyperglycemia and treat obesity-induced IR by enhancing insulin sensitivity." (PMID 39517172, 2024). "Patients with obesity treated with elafibranor showed decreased liver enzymes and improved insulin sensitivity." (PMID 38891828, 2024). "These connections extended from molecular mechanisms, such as DNA damage, to metabolic disruptions like insulin resistance, further encompassing the public health challenge of obesity." (PMID 39484166, 2024). "The increase in fat cell count and accumulation of adipose tissue in obesity leads to heightened release of fatty acids, which disrupts insulin’s action on glucose regulation." (PMID 39876920, 2024). "Consistent with this idea, a differential DNA methylation pattern at the SMYD3 gene was recently found in insulin sensitive women with obesity." (PMID 38148333, 2024). "Previous research on the molecular link between obesity and BC has primarily focused on adipocyte dysfunction, the release of adipokines such as leptin, and hormonal changes involving insulin and peripheral estrogen aromatization in adipose tissues." (PMID 38402239, 2024). "The obesity pathophysiology implies a state of oxidative stress and chronic low-grade inflammation that is highly related to the dysfunction of insulin signaling and lipid metabolism." (PMID 38786759, 2024). "These hormones govern diverse physiological processes like insulin release via incretin and gastrointestinal movement, implying their involvement in the anti-obesity effects of prebiotics." (PMID 38474087, 2024). "Keywords pertinent to the subject “gut microbiota,” “insulin resistance” and “obesity” demonstrated an ascending trend, with 678, 369 and 365 instances in 2024, respectively." (PMID 39211341, 2024). "Increased adiposity is not necessarily deterministic for T2D, given precedent for coexistence of insulin sensitivity with extreme obesity in a small subset of genetic murine models." (PMID 39656538, 2024). "On the one hand, overnutrition, obesity-induced adipose tissue remodeling, insulin level, and hypertension lead to elevated oxidative stress." (PMID 38892574, 2024). "Berberine, an isoquinoline plant alkaloid has been paid more attention due to its anti-obesity activities like insulin sensitizing and anti-inflammatory effects, and its ability to increase energy expenditure by lipolytic and thermogenic actions." (PMID 39058681, 2024). "This diet leads to the development of obesity, peripheral IR, compensatory insulin hypersecretion, and glucose intolerance." (PMID 38704026, 2024). "DPM-1001, an analog of MSI-1436 with an IC50 of 0.1 μM, reverses obesity and improves insulin sensitivity and glucose tolerance in HFD mice." (PMID 39238503, 2024). "The regulation of energy balance is managed by the central nervous system, which integrates satiety cues along with obesity‐related signals like leptin and insulin." (PMID 39606796, 2024). "Such dysregulation of incretin secretion and its downstream effects on pancreatic beta cell insulin secretion is implicated in the pathophysiology of both T2DM and obesity." (PMID 39767626, 2024). "Enhanced insulin sensitivity and protection against diet-induced obesity have been demonstrated in transgenic mice over-expressing GDF15." (PMID 39000187, 2024). "Restoration of insulin signaling pathway such as through the usage of anti-diabetic drugs is a strategy to alleviate obesity-induced neurodegeneration." (PMID 39897964, 2024).
Obesity (continued). "Our previous study revealed that dietary fiber supplementation significantly enhanced insulin sensitivity and effectively mitigated obesity through the modulation of gut microbiota." (PMID 39599615, 2024). "Atopic dermatitis (AD) and obesity have similar pathological manifestations, including inflammation as well as insulin and leptin resistance." (PMID 39564133, 2024). "Compared to the sarcopenia group, men in the sarcopenic obesity group had higher HbA1c, insulin, and HOMA-IR levels, while women had higher fasting glucose, HbA1c, and insulin levels." (PMID 38674866, 2024). "IGFBP-4 is known to have roles in skeletal growth and bone physiology, and in children with obesity, it positively correlates with fasting insulin concentrations." (PMID 38712328, 2024). "A total of 7 studies reported AE + RT to evaluate INS in children and adolescents with overweight/obesity." (PMID 39185113, 2024). "BAT is considered as a source of thermogenesis, which stimulates a healthy phenotype, benefits insulin sensitivity, and acts as a promising target for anti-obesity." (PMID 39590824, 2024). "In contrast to genes involved in focal adhesion, the expression profiles of genes involved in insulin signaling were modulated by obesity in the same direction in all four NVU cell types." (PMID 39456952, 2024). "The carbohydrate–insulin model of obesity places high GI diets as a major driver of the obesity pandemic, responsible for generating hormonal responses that increase fat deposition and produce positive energy balance." (PMID 38731670, 2024). "For instance, the PPARG can regulate systemic insulin resistance, PPARG dysregulation will cause obesity, and HSP90AA1 can inhibit the reduction of adipogenesis through the in vivo pathway to trigger the anti-obesity effect." (PMID 38674532, 2024). "Studies have indicated that the level of AQP7 mRNA expression in prepubertal obese children carrying this mutant gene is lower than that of other prepubertal children with obesity, although their fasting insulin concentration is normal." (PMID 39456161, 2024). "Clinical evidence has shown an association between LBP and central adiposity, a strong risk factor for obesity and type 2 diabetes, as well as BMI, fasting serum insulin, insulin resistance, and metabolic syndrome components, specifically obesity status." (PMID 39421246, 2024). "A prospective cohort study in China indicated that the predictive capacity of the TyG index in forecasting prediabetes surpassed that of obesity, lipid profiles, and other non-insulin-based IR indices." (PMID 39220362, 2024). "Several animal studies have shown that high-sugar diets lead to obesity, insulin resistance, increased intestinal permeability, and low-grade inflammation." (PMID 39540082, 2024). "Previous investigations have shown that specific lipid species (tri-, diacyl-glycerols, ceramides, sphingolipids) can influence insulin sensitivity status of healthy participants, participants with obesity and participants with type 2 diabetes." (PMID 38750012, 2024). "Preperitoneal and Omental fat depots, both related with insulin-resistance comorbidities, share the intraperitoneal space and are included in the classic concept of “visceral” obesity previously assessed by DEXA scan or CT imaging." (PMID 38734755, 2024). "Women with obesity undergoing in vitro Fertilization (IVF) have an altered follicular environment with higher levels of insulin, markers of inflammation, and elevated levels of free fatty acids, which were correlated with abnormal cumulus-oocyte complexes." (PMID 39403129, 2024). "Here, we identify and define the molecular and cellular action of miR-6236, a novel ATM-derived miRNA that influences adipocyte insulin signaling and global glucose homeostasis during obesity." (PMID 38918428, 2024). "Women with obesity have elevated pro-inflammatory chemokines, leptin, and insulin HM content compared to peers with normal weight." (PMID 38544749, 2024).
Obesity (continued). "Before PS overlap weighting, patients initiating GLP-1-RAs had higher rates of diabetic neuropathy and obesity, as well as higher prevalence of insulin, sodium-glucose cotransporter-2 inhibitor, and biologic prescriptions." (PMID 39116084, 2024). "In this line, adiponectin has been the subject of numerous studies analysing the effects of physical exercise and its role in obesity, insulin sensitivity, and low-grade inflammation." (PMID 39058075, 2024). "They manifest the key characteristics of obesity, preserved β-cell function, male predominance, and potential to discontinue insulin therapy, similar to adults with A−β+ KPD." (PMID 38765897, 2024). "In the past, several studies have been conducted to determine how insulin affects the onset of obesity." (PMID 38397458, 2024). "Obesity is a multifactorial disorder characterized by chronic, low-grade inflammation throughout the body, especially in insulin-responsive organs, such as adipose tissues, liver, muscle or the pancreas." (PMID 39004641, 2024). "Here, we tested the role of eosinophils in obesity-related airway hyperresponsiveness that we know to be mediated by insulin and airway nerves." (PMID 39316677, 2024). "The clustering of terms like “DNA-Damage,” “Insulin-Resistance,” and “Obesity” pointed to strong connections between oxidative stress and broader pathological processes." (PMID 39484166, 2024). "Obesity measurements before and during early pregnancy have been identified as strong predictors of fasting insulin concentration throughout pregnancy." (PMID 38764083, 2024). "Altered lipid metabolism is often characteristic of obesity, usually due to elevated circulating lipids and potentially impaired glucose uptake due to insulin resistance." (PMID 38886475, 2024). "The beneficial metabolic effects of SCFAs are mediated by adipose peroxisome proliferator-activated receptor-γ, including preventing high-fat diet-induced (HFD)-obesity and improving insulin sensitivity." (PMID 38257137, 2024). "Our data, combined with previous studies, indicate that small intestine insulin sensitivity is closely related to obesity and that colon GU is more sensitive to training-induced adaptations compared to the small intestine." (PMID 39458548, 2024). "In line with this, in vivo injection of an active IGFBP1 peptide improved insulin sensitivity in a diet-induced obesity mouse model." (PMID 38627562, 2024). "The effects of stress on glucose metabolism are mediated by a variety of hormones that are released in response to stress, which in turn results in elevated blood glucose levels, decreased insulin action, and obesity." (PMID 39457105, 2024). "To date, research has not been able to adequately address the complicated and contentious relationships between insulin and obesity." (PMID 38397458, 2024). "This likely led to overdiagnosis, as obesity generally inhibits the insulin-mediated hepatic release of SHBG, resulting in its reduction." (PMID 39085709, 2024). "Omega-3 PUFAs (also known as n-3 PUFAs) are incorporated into the nervous tissue, improve insulin sensitivity, enhance peripheral glucose utilization, reduce obesity and have anti-atherosclerotic, anti-thrombotic and anti-inflammatory effects." (PMID 38672839, 2024). "Adults with obesity and T2D have lower GLP-1 responses after an oral glucose load than healthy individuals, which associates with worsened insulin sensitivity and impaired β-cell function." (PMID 38087928, 2024). "Regular exercise is widely acknowledged for its positive effects on metabolic parameters, particularly in addressing obesity and enhancing insulin sensitivity." (PMID 38920999, 2024). "Altogether, this suggests that obesity-induced increases in WAT glutaminolysis are linked to attenuated energy expenditure and insulin sensitivity." (PMID 39009762, 2024). "Altogether, these data demonstrate that SUCNR1 plays an essential role in insulin secretion in vivo, particularly in an obesity context." (PMID 38713514, 2024).
Obesity (continued). "Exercise was shown to have favorable effects on metabolic indices (such as blood glucose and insulin levels) related to overweight and obesity acting at various levels." (PMID 39337980, 2024). "Metformin is a commonly used drug for the clinical treatment of T2DM, which improves the sensitivity and utilization of insulin in body tissues and reduces the occurrence of adverse events such as hypoglycemia and obesity." (PMID 38348222, 2024). "SCFAs, final products of dietary ingredients fermented by gut microbiota, have been unveiled to prevent metabolic endotoxemia, protect against inflammation, increase insulin sensitivity, enhance intestinal barrier function, and prevent diet-induced obesity." (PMID 39830328, 2024). "Evidence suggests that deficient nutrition in animals during early life stages can be a precondition for adult individuals to develop metabolic pathologies, such as obesity, hyperglycemia, altered insulin sensibility, and lipid metabolism." (PMID 38536791, 2024). "Natural and synthetic treatments are gaining popularity in managing high-fat diet (HFD)-induced obesity, such as those increasing insulin sensitivity and secretion while reducing glucose levels." (PMID 39065712, 2024). "Another study found that adolescents with obesity who had a monophasic glucose response had lower insulin sensitivity and impaired β-cell function compared to those with a biphasic response, despite similar FPG and 2hrPG in the two groups." (PMID 38576510, 2024). "This metabolically harmful NK population expands in obesity and secretes tumor necrosis factor alpha (TNFα), which ignites low-grade inflammation, increases plasma IL-6 levels, and impairs insulin sensitivity." (PMID 38474057, 2024). "Conditions such as obesity, inflammation, hyperglycemia, and dyslipidemia can reduce insulin permeability across the BBB." (PMID 39596023, 2024). "It shows a higher rate of microvascular complications, macrovascular complications, obesity, and insulin use in the Black patients." (PMID 38667608, 2024). "In a cohort of 60 lactating women (half of them with overweight/obesity), six miRNAs known to be involved in adipogenesis and insulin signaling were screened for potential effects on infant growth depending on their levels in milk." (PMID 38786092, 2024). "PCOS is a metabolic disease characterized by higher androgen and is often accompanied by metabolic disorders, such as insulin tolerance, hyperglycemia, and obesity, which can lead to infertility in severe cases." (PMID 38990031, 2024). "The prevalence of obesity (BMI ≥ 25 kg/m2) was 33.3% (Early; n = 5, Late; n = 3), but their insulin secretory capacity was preserved." (PMID 39049060, 2024). "Their ability to enhance thermogenesis, improve insulin sensitivity, and influence lipid metabolism makes them promising targets for therapeutic interventions in obesity and metabolic disorders." (PMID 39335642, 2024). "Obesity led to an elevation in insulin levels, possibly contributing to greater fat accumulation and increased adiposity." (PMID 39207362, 2024). "The mechanisms linking oxidative stress to obesity involve detrimental effects on adipocyte function, insulin resistance, chronic inflammation, and dysregulated lipid metabolism." (PMID 38391792, 2024). "A recent systemic review and meta-analysis published in 2023 showed the positive effects of exercise interventions on insulin resistance in children and adolescents with overweight and obesity." (PMID 39822775, 2024). "Substantial changes occur within the adipose tissue microenvironment during the development of obesity due to a combination of adipogenesis and lipogenesis, processes regulated by insulin/insulin resistance signaling." (PMID 38541912, 2024). "The high fructose promoted insulin sensitivity and obesity, while trans fats exacerbated hepatic steatosis and were associated with necroinflammatory changes." (PMID 39339720, 2024).